MMP9 (matrix metallopeptidase 9)
Diseases named in the same sentence as MMP9 in open-access papers (continued):
Sharing a sentence is not in itself a finding about the gene and the disease.
cancer (continued). "It included a number of genes with obvious cancer relevance including CD44, catenin b1 (CTNNB1), vimentin (VIM), cathepsins B and S (CTSB, CTSS), MMP9, XIAP, JunD, numerous proto-oncogenes (REL, YES, SET, FGR, CRK), and HSP90AA1 (which is a chaperone which stabilizes MIF as a client)." (PMID 28957348, 2017). "Fibroblasts did not express appreciable MMP9 levels but rather enhanced production of MMP9 by carcinoma cells via cytokine signaling crosstalk." (PMID 28423685, 2017). "Given that S100A4 is an established metastasis-promoting protein, it is not surprising that this S100A4/MMP9 pathway is demonstrated in other cancer types." (PMID 27127879, 2016). "Although MMP2 and MMP9 have been shown to be upregulated in many cancers and enriched at the invadopodia, there are no defined pathways that describe how these enzymes are transported to specific ECM degradation sites that facilitate metastasis." (PMID 27789576, 2016). "Importantly, MMP2, MMP9 and MMP14 are enriched at the invadopodia and are required for cancer metastasis." (PMID 27789576, 2016). "They concluded that the inhibition of cancer cell invasion by cyanidin 3-glucoside or peonidin 3-glucoside, may be due to a downregulation of MMP-2, MMP-9 or u-PA expression of various cancer cells." (PMID 27548122, 2016). "This type of neutrophil may contribute to cancer progression, since it produces growth factors such as vascular endothelial growth factor (VEGF), hepatocyte growth factor (HGF), MMP9, Bv8, and also have the capability to suppress cytotoxic lymphocytes." (PMID 27863478, 2016). "Treatment with BJ-1113 significantly suppressed the 5-HT-enhanced expressions of TPH1, MMP-9, and VEGF, and consequently, the secretions of VEGF and 5-HT, suggesting that BJ-1113 suppresses cancer progression by inhibiting VEGF expression and the autocrine function of 5-HT." (PMID 27871326, 2016). "Significant upregulation of expression of 3 target genes (MMP9, PLAUR and SERPINE1) of miR-204 had been observed in cancer tissues as expected since it is known that downregulated expression of miRNAs may upregulate expression of target genes." (PMID 27597234, 2016). "Given that it remains unclear how miR-204 affects the cancer invasion machinery, we decided to investigate whether miR-204 inhibits MMP2 and MMP9 targeting to invadopodia by decreasing cellular levels of Rab40b." (PMID 27789576, 2016). "p38α also induces the expression of MMP1, MMP2, MMP9 and MMP13 in other types of cancer." (PMID 27286263, 2016). "Alternatively, different cancers might preferentially use either the MMP2 and MMP9, or MMP14 targeting pathways." (PMID 27789576, 2016). "Furthermore, by using specific inhibitors of various cancer-related signaling pathways, we showed that 14-3-3β-induced up-regulation of MMP2 and MMP9 was dependent on PI3K/Akt/NF-κB signaling pathway." (PMID 26730736, 2016). "The overexpression of many MMP family members, such as MMP1, MMP2, MMP7, MMP9, and MMP11 has been found to be involved in cancer progression; therefore, the development of MMP inhibitors has become an effective strategy in clinical cancer therapies." (PMID 26084486, 2015). "Decursin and decursinol angelate from A. gigas inhibit not only NO production and NO-induced inflammation by suppressing MMP-9, iNOS, IL-1β, and TNF-α expression but they also demonstrate anti-cancer effects by inhibiting cell proliferation and activating apoptosis." (PMID 26083119, 2015). "The angiogenic and invasive effects of PARVA-induced signalling in cancer cells might be attributed to the PI3K–Akt pathway rather than to the increase in NADPH expression, although the MMP9 level was elevated in these cells." (PMID 25738875, 2015). "In various cancer cells, TGF-β-induced EMT could upregulate the expression of MMP-2 and MMP-9, the two most critical enzymes, by activating the transcription factor Slug and Snail." (PMID 25879017, 2015).
cancer (continued). "Our results demonstrated that MMP-9 and uPA activities in 4T1 cells were reduced when treated with RA-XII for at least 48 hours, suggesting that RA-XII is able to inhibit ECM degradation and hence cancer cell invasion." (PMID 26592552, 2015). "In addition, fibronectin, matrix metalloproteinase-9 (MMP9) and E-cadherin were essential components in EGFR/PTX3-mediated cancer metastasis." (PMID 25797258, 2015). "Moreover, nifuroxazide markedly blocked cancer cell migration and invasion, and the reduction of phosphorylated-Stat3Tyr705, matrix metalloproteinase (MMP) MMP-2 and MMP-9 expression were also observed." (PMID 25811798, 2015). "In stem cells and cancer cells, MMP2 and MMP9 are regulated by cytokines such as TGFβ2 and TNFα." (PMID 25774514, 2015). "NF-κB pathway plays an important role in regulating cancer cells proliferation, anti-apoptosis, invasion and metastasis and angiogenesis, through modulating series of functional genes expression and activity, including IL1A, CCND1, MYC, Bcl-2, MMP9 and VEGF." (PMID 26429874, 2015). "In addition, inhibition of AKT phosphorylation has been correlated with the inhibition of cancer cell invasion by reducing MMP-2 and MMP-9 expression." (PMID 25647359, 2015). "MMPs have been recognized as involved in cancer invasion and metastasis, especially MMP2 and MMP9." (PMID 26714817, 2015). "AR, MMP-2 and MMP-9 may be predictive markers for HCC and could be regarded as candidates for indicating the cancer stage." (PMID 25667651, 2015). "Cancer cell invasion may require the secretion of MMPs such as MMP-2 and MMP-9 to degrade the matrigel." (PMID 25798926, 2015). "Also, it has been shown that cancer cells can induce expression of proteolytic enzymes such as MMP-2, MMP-9 and urokinase in adjacent fibroblasts through paracrine signalling." (PMID 26219353, 2015). "In cancer cells, the OPN/MMP-9 signaling pathway has been reported." (PMID 26289107, 2015). "Furthermore, the density of cells expressing matrix metalloproteinase-9 (MMP9), a marker correlating with invasive capacity in carcinomas, was also significantly reduced by 61% in shRNA tumors compared to control tumors (P < 0.05)." (PMID 26452220, 2015). "MMP-9 and MMP-2 expression levels are significantly elevated in a range of carcinomas." (PMID 26098839, 2015). "Besides, our results indicated that solanine can also inhibit the process of metastasis by downregulating the expression of cancer cells migration related proteases, MMP-2 and MMP-9." (PMID 24949471, 2014). "In addition, NF-κB controls the critical genes including COX-2, Bcl-2, and genes required for invasion and angiogenesis such as MMP9 and VEGF in the early and late stages of aggressive cancer." (PMID 24845412, 2014). "Several well-differentiated HCC cells express MT1-MMP and gradually small amounts of MMP-2 and MMP-9, probably stimulated by inflammatory cytokines or TGF-β, which may participate in the stromal invasion or the formation of the thick capsule of cancer nodules." (PMID 24978432, 2014). "It is likely, therefore, that altered patterns of miR expression may also facilitate the differential expression of gelatinase B/MMP-9 and TIMP-1 in malignant tumours." (PMID 24473089, 2014). "All the examined small compounds demonstrated anticancer activity in the in vitro experiments and may impact cancer cells by acting on AKR1B10, MMP-9 and their targets." (PMID 24348813, 2014). "In this study, MMP9 levels were higher in patients with malignant tumor than benign group but the difference was not significant." (PMID 25469360, 2014). "The levels of MMP-2 and MMP-9 were significantly higher in carcinomas than in peritumoral tissue, irrespective of MMP type or activity state." (PMID 24778099, 2014). "In addition, we provide evidence that miR-124-3p appears to play an important role in epithelial mesenchymal transfer (EMT), and modulates the expression of genes which promote cancer metastasis, such as MMP2, MMP9, c-Met." (PMID 24180482, 2013).
cancer (continued). "MMP2 and MMP9 are involved in intravasation by participating in extracellular matrix (ECM) conversion and remodeling through hydrolyzing major protein components when cancer cells must exit the blood vessels, lymphatics and constricted capsules." (PMID 24023875, 2013). "The suppression of the matrix metalloproteinases MMP2 and MMP9 and the inhibition of the enzymatic activities of these metalloproteinases further confirmed the antimetastatic and antiinvasive activities of HCA in highly metastatic cancer cells." (PMID 23860239, 2013). "MMP-9 was not expressed in the normal oral mucosa or dysplasia, whereas in situ carcinomas were weakly detectable." (PMID 23365550, 2013). "With regard to MMP-9/NGAL complex, recent evidence suggests that urinary detection of the complex may represent a new biomarker for the prediction of cancer disease." (PMID 23760084, 2013). "In addition, the levels of phosphorylated retinoblastoma (pRB, a downstream effector of cyclin D1) and matrix metalloproteinase 9 (MMP-9, a downstream gene of Ets1) were decreased in miR-9 over-expressing cancer cells." (PMID 23383271, 2013). "The decrease in MMP-9 secretion following treatment with siRNA anti-Rac3 can also be involved in its inhibitory effect on VM in MDA-MB-231 cells, as it was described that both MMP-2 and MMP-9 play an important role in VM in cancers." (PMID 23388133, 2013). "Reducing M2 macrophage characteristics systemically may provide advantages to cancer patients because they express much lower levels of TGFβ, VEGFA, VEGFC, MMP-9, and MMP-1." (PMID 23667623, 2013). "In cancer cells, MMP-2 and MMP-9 are controlled by their endogenous inhibitors TIMP-1 and TIMP-2." (PMID 23878609, 2013). "It was previously demonstrated that the ~125 kDa MMP activity in the urine of cancer patients is a complex of MMP-9 and NGAL, which may represent a new biomarker for the prediction of cancer disease." (PMID 23672427, 2013). "Several MMP species were detected in urine from cancer patients including MMP-2, MMP-9, MMP-9/NGAL." (PMID 23672427, 2013). "Although there are no reports on the effects of 4N1K on MMP-9 expression in human cancer patients, these findings support our observation." (PMID 22928942, 2012). "MMP-2 and MMP-9 play important roles in the degradation of the ECM, including type IV collagen, and their activity and expression are correlated with metastatic abilities and prognosis of cancer." (PMID 22420896, 2012). "Therefore, it appears that FAK can promote CL1-5 cancer cell migration through the MAPK signaling and MMP-2 and MMP-9 pathway." (PMID 22454661, 2012). "MMP-9 was elevated compared to cancer control tissue in all groups, but this was not significant in any comparison." (PMID 23300643, 2012). "An influence of WIN on the regulation of MMP-9 was described for cancer cell lines, but so far not for cells of the immune system." (PMID 23139770, 2012). "New approaches to target MMP-9/NGAL are needed as MMP-9 inhibitors have not performed well in clinical cancer trials and NGAL has functions which are independent of MMP-9." (PMID 23100449, 2012). "Radiotherapy, the most common mode of treating cancer, has been reported to elicit an activated phenotype that promotes rapid and persistent remodeling of the extracellular matrix (ECM) through the induction of proteases like MMP-9, uPA and uPAR." (PMID 22984561, 2012). "For the purposes of the microarray data validation, we have selected 9 genes that may play the most important role in cancer cells-macrophages interactions: CCL2, CCL3, CD163, CSF1R, HIF1, Il-18, MMP9, VEGF-C, and Wnt7b." (PMID 22353646, 2012). "This study demonstrated a significant difference between plasma MMP9 levels in cancer patients compared with controls but no such difference for serum levels." (PMID 22433968, 2012). "Kaplan-Meier analysis of survival curves showed significantly worse survival for patients with positive MMP-9 staining than for those with MMP-9 negative cancers." (PMID 23202950, 2012).
cancer (continued). "Given the important role of Runx2 in cancer-induced angiogenesis and metastasis, we wondered whether it plays a role in the inhibition of MMP-2 and MMP-9 expression induced by LGD1069." (PMID 21649908, 2011). "MMP-9 and MMP-2 play critical roles in the degradation of type IV collagen, a major constituent of the basement membrane, and are closely related to the invasion and metastasis of various cancer cells." (PMID 21738655, 2011). "Consistently with the changes in the invasive behaviour of the cells, we found that increased expression of XRCC3 resulted in increased activity of MMP-9, a gelatinase involved in the extracellular matrix (ECM) degradation that is thought to play an important role in cancer metastasis." (PMID 21283680, 2011). "IGFBP1 levels were significantly higher in cancer serum (p-value = 0.0097) while MMP9 levels were not (p-value = 0.20)." (PMID 20559444, 2010). "Firstly, THL could inhibit, in cancer cells, the expression and secretion of MMP-2, MMP-9, and uPA, which involve in degradation of extracellular matrix and play important roles in cancer cell migration and invasion." (PMID 20429953, 2010). "Regarding MMP-9/NGAL, current evidence suggests that urinary detection of the complex may represent a new biomarker for the prediction of cancer disease." (PMID 19889214, 2009). "Even though the detection of NGAL and MMP-9/NGAL complex in systemic circulation is likely to directly reflect their tissue expression, scarce data are currently available on the significance of their serum measurement in cancer disease." (PMID 19889214, 2009). "Such anti-cancer activities of BER involved suppression of Akt and NF-κB signaling and its upstream and downstream targets by reducing expressions of the related proteins and mRNA as well as pro-MMP-9/pro-MMP-2 activation in the cells." (PMID 19796390, 2009). "TNF-α has been shown to upregulate MMP-9 gene expression in malignant carcinoma via TNF-R1, and TNF-R1 but not TNF-R2 has been shown to be important in inflammatory responses involving IL-1β and MMP-3 and -9 in murine brain injury." (PMID 19435506, 2009). "In conclusion, our findings raise the possibility that EGCG could inhibits cancer cell invasion through reversal of hypermethylation status of RECK and downregulation of MMP-2 and MMP-9." (PMID 18665171, 2008). "Treatment with 50 μM EGCG did not cause downregulation in MMP-9 activity but MMP-2 in HSC4 and SCC25 cancer cell line (data not shown)." (PMID 18665171, 2008). "High Bryne malignancy score value predicted high level of αvβ6-integrin (OR 2.9, 95% CI 1.1–8.2), but MMP-9 and COX2 levels in carcinoma cells (OR 0.17, 95% CI 0.03–0.78; and OR 0.19, 95% CI 0.06–0.65, respectively) were negatively associated with high Bryne category." (PMID 18253113, 2008). "The ability of spheroids to contribute to the spread of cancer has been assessed by growth, adherence and disaggregation capabilities and by investigating the profile of integrins and MMP2/MMP9 that may mediate the dissemination process." (PMID 17567918, 2007). "Notably, lidocaine may modulate NET formation and, in a few studies published so far, was shown to reduce postoperative NET markers and other pro-metastatic factors (MMP-9, VEGF) in cancer surgery." (PMID 41516032, 2025). "On the contrary, MMP9 seemed completely nonspecific and not correlated to an increase in cancer cell aggressiveness, while other genes such as VIM, CDH5, and MCAM showed a trend toward an increased expression in the metastatic counterpart, albeit not statistically significant." (PMID 40332096, 2025). "Thus, we can observe that, unlike the other metalloproteinases, MMP-9 plays a significant role as a biomarker in almost all types of cancers and various other diseases." (PMID 41002342, 2025). "Furthermore, cancer cells in the p-EMT state showed upregulated expression of MT1-MMP and MMP-9." (PMID 40244200, 2025).
cancer (continued). "In addition, HIF-1α upregulates other genes whose products contribute to cancer cell invasiveness, such as IL-8, VEGF, and matrix metalloproteinase-9 (MMP-9), responsible for proteolytic cleavage of vascular basement membranes, clearing the way for mesenchymal-like cancer cells to disseminate." (PMID 40710312, 2025). "However, in vivo studies in mouse cancer models suggest that TSPAN8 enhances cancer cell motility and migration mainly by recruiting integrins, whereas CD151 efficiently recruits and activates MMP9 and MMP13 to facilitate the degradation of the ECM and the invasion of tumor cells." (PMID 38275818, 2024). "Moreover, HMHA1 overexpression remarkably enhanced the total gelatinolytic activities by extracellular MMP-2 and MMP-9, suggesting that HMHA1 may promote ECM degradation and thereby facilitates hypoxic cancer cell invasion." (PMID 38740970, 2024). "Moreover, calycosin inhibited the proliferation, invasion, and migration of cancer cells through decreasing MMP‐2, MMP‐9, and CD147 levels through downregulating BATF (basic leucine zipper ATF‐like transcription factor) expression and TGFβ1 (transforming growth factor 1) expression." (PMID 38230908, 2024). "Moreover, overexpression of MMP-9 and Vimentin implicates local aggressive behavior of tumors and inhibition of MMP-9 and Vimentin can suppress the migratory and invasive abilities in cancer." (PMID 38554175, 2024). "MMP-9 has been identified in EVs in different physiological and pathophysiological processes, from pro-angiogenic breakdown of capillary membranes and localized proteolysis and degradation of the ECM during metastasis and cellular migration, to Alzheimer’s disease and cancer progression." (PMID 38398037, 2024). "This review provides a comprehensive overview of the anti-cancer potential of the most common single polyphenolic compounds, such as curcumin, resveratrol, epigallocatechin-3-gallate (EGCG), quercetin, and genistein, known to modulate the activity and expression of MMP-2 and MMP-9." (PMID 39335164, 2024). "The search included all studies published until May 2024 and used the following keywords, alone or in combination: cancer, cancer diseases, curcumin, EGCG, genistein, quercetin, resveratrol, polyphenols, polyphenolic compounds, chemoprevention, MMP-2, MMP-9, gelatinases, type IV collagenases." (PMID 39335164, 2024). "Finally, we also analyzed the roles of MMP9 and SCGN in pan-cancer." (PMID 38375034, 2024). "However, eHsp90 is primarily known for enhancing the invasiveness of cancer cells by interacting with ECM proteins and ECM-modifying proteins present in the TME, such as Matrix Metalloproteinase (MMP)-2, MMP9, Plasminogen, Collagen-1, Fibronectin (FN), and LOX-like protein-2 (LOXL2)." (PMID 39594828, 2024). "We showed that IL-8 expression in cancer nests significantly correlated with CD204 positive macrophage infiltration, suggesting that TAMs induced IL-8 expression and may have some relation to MMP9 expression in cancer cells." (PMID 37296952, 2023). "EA could inhibit the metastasis by downregulating MMP-2 and MMP-9 expression since matrix metalloproteinases (MMPs) are endopeptidases, capable of extracellular matrix (ECM) degradation, hence promoting migration, invasion, and metastasis of cancer cells." (PMID 37259418, 2023). "In addition, MDSCs facilitate cancer progression and metastasis in a nonimmune manner by producing MMP-9, which is a primary regulator of EMT, as well as VEGF, in order to promote TME remodelling and angiogenesis." (PMID 37480104, 2023).